SMAD4 (SMAD family member 4)
Diseases named in the same sentence as SMAD4 in open-access papers (continued):
Sharing a sentence is not in itself a finding about the gene and the disease.
tumor (continued). "TGF-β, particularly when tumor-suppressive SMAD4 pathways are lost, induces myofibroblastic fibroblast (myCAF) expansion and an immunosuppressive niche that fosters tumor-cell escape and dissemination." (PMID 41394398, 2025). "Nuclear expression of SMAD4 was detected in less than half of tumor cells in TA but showed diffuse moderate expression in carcinoma cells." (PMID 39936166, 2025). "Corroborating a potentially tumor-suppressive versus tumor-promoting function of SMAD4 in the liver versus lungs, 69% of cases with recurrent liver metastases lacked SMAD4 expression, in contrast to 50% of concurrent and 33% of isolated lung metastases." (PMID 40999053, 2025). "By analyzing human tissue samples and cellular models, we found that higher SMAD4 expression correlates with early-stage OSCC and epithelial markers, while decreased SMAD4 is associated with increased mesenchymal markers and tumor invasiveness." (PMID 40507242, 2025). "SMAD4 participates in tumor metastasis and infiltration by transcriptionally regulating transforming growth factor beta (TGF-β) signaling pathway, such as MMP7 and N-cadherin, and was enriched in the PPI network we constructed." (PMID 41170449, 2025). "RT-PCR analysis evaluated the mRNA levels of EMT markers and Smad4 in tumor and healthy tissues (n = 23)." (PMID 40507242, 2025). "RUNX3 plays a crucial role in TGF-β signaling via binding with Smad family including Smad2, Smad3 and Smad4 and tumor suppression pathways." (PMID 40354349, 2025). "Hepatocyte-specific Smad4 deletion in mice reduced liver tumors, fibrosis, and myeloid-derived suppressor cell infiltration while enhancing anti-tumor immunity." (PMID 40260391, 2025). "Specifically, MUC1 regulates the TGF-β1 function switching from a tumor-suppressor to a tumor-promoter through phosphorylation of its C-terminal tyrosines independently by SMAD4 signaling." (PMID 40001578, 2025). "Smad4, a critical tumor suppressor gene, plays a significant role in pancreatic biology and tumorigenesis." (PMID 39596873, 2024). "This aligns with dual roles of SMAD4 across malignancies and in different stages of tumor progression." (PMID 38383727, 2024). "Tumor cell expression of MYO1F was increased to a greater degree by BMP4 in the presence of SMAD4 than in its absence." (PMID 38689334, 2024). "SMAD4 is a tumor suppressor and a key regulator of the transforming growth factor (TGF)-β signaling pathway." (PMID 39682280, 2024). "Given that Smad4 is induced by Pten knockout and constrains tumor progression, we compared the DEGs after Klf5KR knockin with those caused by Smad4 knockout." (PMID 38781024, 2024). "Studies have shown that SMAD4 exerts its tumor-suppressive effects in CRC by downregulating the expression of the key inflammatory mediator CCL20." (PMID 39164192, 2024). "The TGF-β/Smad4 signaling pathway is further recognized for its regulation of key biological processes, including epithelial–mesenchymal transition, DNA damage response, and microRNA regulation, with Smad4 acting as a crucial tumor suppressor." (PMID 39596873, 2024).
tumor (continued). "The patient’s tumor was found to contain somatic mutations in APC (p.Q1549*), APC (p.R904fs), SMAD4 (p.R135*), SMAD4 (p.A190fs), ATR (p.F134fs) and KRAS (p.G12D)." (PMID 38243056, 2024). "In summary, the role of SMAD4 in CRC is not limited to inhibiting tumor cell proliferation but also includes the regulation of tumor cell migration and invasion capabilities." (PMID 39164192, 2024). "Our work demonstrated that SMAD4 can promote the aggressive tumor behavior and induce NE phenotype and EGFR-TKI and pemetrexed resistance independently of RB1 status for the first time." (PMID 38233864, 2024). "Using injected LY2 cells, cells derived from 4NQO treatment, or cells with a SMAD-4 mutation to overexpress TGF-β, this study found a durable reduction in mouse tumor size and identified immune permissive tumor niches that promoted therapy response." (PMID 39272905, 2024). "We will analyze how SMAD4 protein regulates tumor growth, apoptosis, angiogenesis, and invasiveness by affecting the TGF-β signaling pathway." (PMID 39164192, 2024). "In in vivo experiments, we also observed the significantly increased tumor growth and tumor weight when SMAD4 was knocked out, which was consistent with the results of in vitro experiment." (PMID 38233864, 2024). "There was a positive correlation between the increased Smad4 expression and tumor grades, indicating that the Smad4 expression was higher in patients with advanced HCC." (PMID 39346534, 2024). "Transwell, colony formation, and CCK‐8 assays were further carried out to verify the relationship between IBSP and SMAD4 in tumor cells." (PMID 39118232, 2024). "Loss of SMAD4, which occurs late in pancreatic tumorigenesis, promotes cancer cell proliferation and motility by the dysregulation of the TGF-β pathway, causing tumor chemoresistance, invasion and metastasis, immune evasion, etc.." (PMID 39682280, 2024). "Silencing IBSP (si‐IBSP) mitigated the effects of SMAD4‐induced tumor proliferation, confirming that IBSP acts as a downstream target of SMAD4 in the BMP signaling pathway." (PMID 39118232, 2024). "SMAD4 is a central mediator that regulates cellular processes such as growth, apoptosis, and migration, affecting tumour initiation and progression." (PMID 39589938, 2024). "The results indicate MET, ERBB2, SMAD4, and CCNE1 copy-number status is significantly associated with primary tumor site." (PMID 39062773, 2024). "SMAD4-209 is coding for full-length SMAD4 protein and contributes to the SMAD4 protein pull with a tumor-suppressive role and maintenance of tissue homeostasis and cell cycle regulation." (PMID 39132157, 2024). "GSTO2 and MT1M have been described as tumor suppressors in cancer, and SMAD4 is listed as a tumor suppressor gene in the COSMIC Cancer Gene Census." (PMID 38751776, 2024). "Altogether, these data clearly suggest that the absence of RAC1b or TAp73 impairs TGF-β signaling toward the tumor-suppressing SMAD4-dependent pathway." (PMID 38255305, 2024). "The next-generation sequencing has shown PIK3CA E545K, SMAD4 1309-1G, and ALK E717K gene mutations, receptor tyrosine kinase 2 (ErbB-2) amplification, microsatellite stability, and low tumor mutational burden of 6.3 mutations per megabase." (PMID 38215117, 2024). "We further elucidate the tumor’s metastatic potential through the lens of cellular pathways exploitation, notably those regulated by SMAD4." (PMID 38975339, 2024). "In contrast, Xiong et al64 observed a substantial infiltration of CD3+, CD4+, and CD8+ cells into Smad4 KO tumor tissues." (PMID 40458305, 2024). "In summary, our research elucidates that SMAD4 can enhance the cytotoxic activity of human NK cells against CRC tumor cells." (PMID 39439794, 2024).
tumor (continued). "Reduced gene expression of GSTO2, SMAD4, and MT1M was also significantly associated with high-grade tumor histology (Gleason grade group ≥ 8) in NKX3-1-loss tumors." (PMID 38751776, 2024). "SMAD4 is a tumor suppressor and a crucial component of the transforming growth factor-β (TGF-β) signaling pathway, playing significant roles in cell proliferation, differentiation, migration, apoptosis, and interaction with stromal inflammatory cells." (PMID 39113889, 2024). "The TGF-β pathway is an important pathway in the development of metastasis in CRC and has been reported to be linked to the loss of SMAD4, a transcription factor in TGF-β superfamily signaling that promotes tumor growth." (PMID 38213716, 2024). "As investigations into tumor immunotherapy progress, the influence of mothers against decapentaplegic homolog 4 (SMAD4) on immune cells is increasingly coming to light." (PMID 39439794, 2024). "In the TME, Smad4 acts indirectly on anti-tumor immune response by regulating the transcription of multiple chemokines." (PMID 39346534, 2024). "Recently, a study identified a novel histone deacetylase 5 (HDAC5)-CCL2/CCR2-TGF-β/SMAD4 axis driven by epigenetic regulation to promote tumor growth in a PDAC model." (PMID 38167055, 2024). "In summary, these finding suggest that SMAD4 has the potential to enhance the cytotoxic activity of NK cells on CRC tumor cells." (PMID 39439794, 2024). "In laryngeal squamous cell carcinoma (LSCC), miR301a-3p acts as a cancer-promoting gene, targeting multiple tumor suppressor genes, such as Smad4." (PMID 38238286, 2024). "Immunohistochemical and western blot analysis demonstrated that Smad4 expression in tumor tissues was significantly higher than in normal tissues." (PMID 39346534, 2024). "TGF-β exercises tumor resistance by promoting the transcription factors Smad2 and Smad3 to connect Smad4 to transmit signals." (PMID 38590651, 2024). "Mutations in SMAD2 and SMAD4 genes have been observed in CRCs; additionally, SMAD4 copy number loss was detected in CRC patients and was associated with tumor progression, while SMAD7 was shown to be deleted or amplified in CRC." (PMID 38542469, 2024). "The study demonstrated that hepatocyte-specific Smad4 deletion reduced tumor incidence after diethylnitrosamine (DEN) and carbon tetrachloride (CCl4) treatment." (PMID 39346534, 2024). "A key tumor suppressor gene involved in the TGF-β-signaling pathway is mothers against decapentaplegic homolog 4 (SMAD4)." (PMID 39795864, 2024). "The SMAD4 gene acts as a tumor suppressor gene, inhibiting the proliferation, invasion, and metastasis of tumor cells." (PMID 39164192, 2024). "Our results confirmed that tumor cohesion was weakened by BI sup, leading to increased levels of SMAD4 and TGF-beta and the regulation of EMT-related genes." (PMID 39113194, 2024).
tumor (continued). "SMAD4, a primary tumor suppressor gene, is a pivotal component of the transforming growth factor beta 1 (TGFB1) pathway." (PMID 39113194, 2024). "In this study, we demonstrates that SMAD4 enhances the cytotoxic activity of human NK cells against CRC tumor cells." (PMID 39439794, 2024). "In essence, TGF-β drives SMAD4 signaling more effectively to protect tumor growth when KRAS is strongly inhibited." (PMID 38167055, 2024). "Consistently, double immunofluorescence staining indicated that Smad4 was highly expressed in albumin+ hepatocytes in mouse HCC tumor tissues." (PMID 39346534, 2024). "Consistently, tumor size and weight dramatically increased in the SMAD4-KO group but decreased in the control group after treatment with TAM or FVE for 6 weeks." (PMID 38914552, 2024). "Patients with nHM tumours with SMAD4 deletion had shorter RFS (HR = 2.13, 95% CI = 1.04–4.34), and those with TCF7L2 translocation had shorter OS (HR = 4.82, 95% CI = 2.10–11.03) and RFS (HR = 7.50, 95% CI = 2.72–20.69)." (PMID 39112715, 2024). "SMAD4 is a tumor suppressor gene that has been demonstrated to regulate cell proliferation and differentiation as well as interfere with the immune responses in PDAC." (PMID 38280995, 2024). "In terms of cell proliferation, SMAD4 mediates tumor-suppressive signals under normal circumstances, thereby inhibiting the excessive proliferation of tumor cells." (PMID 39164192, 2024). "In nHM tumours, most driver genes, particularly SMAD4, SMAD2 and FBXW7, correlated with high hypoxia." (PMID 39112715, 2024). "The MSI class 1 tumours more often had ARID2 mutations, while class 2 had more BRAF and SMAD4 CNVs, FOXP2 amplifications and 7q11 gains." (PMID 39112715, 2024). "We revealed that upstream transcription factor SMAD4 enhances the translation of downstream IBSP that can promote tumor migration and invasion." (PMID 39118232, 2024). "Since BMP4 is a secreted protein, we conclude that it can act both in an autocrine manner in SMAD4-expressing tumor cells and in a paracrine manner on stromal cells to suppress metastasis." (PMID 38689334, 2024). "Interactions between the TGF-β/Smad4 pathway and other signaling cascades like MAP kinase, PI3K/Akt/mTOR, and WNT/β-catenin are particularly significant in tumor formation and progression, pointing to Smad4 as a potential target for cancer therapies." (PMID 39596873, 2024). "It works by suppressing Wnt, β-catenin, and SMAD4, resulting in decreased tumor cell proliferation and differentiation." (PMID 37265908, 2023). "Lin found that miR-210 secreted by HCC cells can promote tumor angiogenesis by targeting SMAD4 and STAT6 to endothelial cells." (PMID 37914951, 2023). "In combination with gemcitabine, DTLL exhibits a unique mechanism of action similar to that of SMAD4/DPC4, showing superior inhibition of the growth of gemcitabine-resistant/sensitive tumours." (PMID 37685308, 2023). "None of the established risk factors, including age, gender, tumour size, tumour differentiation, T stage, N stage, M stage, TNM stage, neural invasion and cancer thrombus, were found to correlate with SMAD4 expression in iCCA, pCCA and dCCA." (PMID 37488750, 2023). "It is known that the SMAD4 gene is involved in gene regulation and tumor suppression via the TGF-β pathway." (PMID 37049199, 2023).
tumor (continued). "In PDAC, the effect of TGF-β1-induced autophagy on tumours was dependent on the alteration of SMAD4/DPC4." (PMID 37685308, 2023). "As SMAD4 reduces CXCL1 expression by decreasing inhibitor of NF-κB kinase β (IKKβ) activity and affecting glycogen synthase kinase-3β (GSK-3β), a decrease in SMAD4 expression in a tumor cell increases CXCL1 expression." (PMID 37408240, 2023). "In contrast, tumor organoids re-expressing SMAD4 only saw 10 colonies, showing a lower efficiency of penetration through transwell membranes." (PMID 38136364, 2023). "At present, research on SMAD4 is mainly focused on its role as a target of tumor therapy, but some studies have confirmed that this protein also has activity in the late stage of COVID-19 infection." (PMID 37457560, 2023). "IRS-1 and 2 and SMAD4 expression was evenly distributed in tumor epithelial cells, spindle shaped cells/stromal cells, and immune cells." (PMID 36900240, 2023). "High expression of IRS1 in stromal tissue and RUNX3 and SMAD4 in both stromal and tumor tissue were positive prognostic factors." (PMID 36900240, 2023). "The findings revealed a reduction in the expression of both SMAD4 and STING1 in tumour samples, along with a significant correlation between the expressions of SMAD4 and STING1." (PMID 37488750, 2023). "In conclusion, our study has provided evidence that the expression of both STING1 and SMAD4 is downregulated in CCA tumour tissues when compared to the corresponding para‐tumour tissues." (PMID 37488750, 2023). "Since tumor organoids grew independently of extracellular matrix, it was important to determine how the expression of SMAD4 would alter the transcriptome in this new extracellular environment." (PMID 38136364, 2023). "Histopathological observation also showed that no apparent damages were observed in the parenchyma organs of tumor-bearing mice in all groups, which exhibited the low toxicity of the Smad4 mRNA nano-lantern." (PMID 36894556, 2023). "Intriguingly, among these co-regulated functional categories, GATA2 and SMAD4 jointly modulated the expression of genes involved in multiple cancer-promoting pathways particularly like TGFβ signaling that is required for tumor invasiveness and metastasis." (PMID 37550764, 2023). "Upon investigation of the mechanism of the therapeutic effects of luteolin, we found that luteolin reduced tumor cell proliferation and differentiation, as indicated by the suppression of Wnt, β-catenin, and SMAD4." (PMID 37265908, 2023). "We used another part of the tumor tissue to assess gene and protein expression of Wnt, β-catenin, E-cadherin, and SMAD4." (PMID 37265908, 2023). "Collectively, these findings unveil an unprecedented antagonistic interaction between the tumor suppressors Smad4 and Prdm16 that functions to restrict PDAC progression and metastasis." (PMID 36828547, 2023). "SMAD4 is a tumour suppressor and participates in the regulation of the transforming growth factor β (TGF‐β) signalling pathway." (PMID 37488750, 2023). "Gene expression was evaluated in treated and untreated tumor cells; it was observed that the treatments with EC (300 μM) induced higher expression of the anti-proliferative genes Cdh1, Mtss1, Pten, Bmrs, Fat1, Smad4, and Nrf2." (PMID 37687058, 2023).